CD40 (CD40 molecule)
Diseases named in the same sentence as CD40 in open-access papers (continued):
Sharing a sentence is not in itself a finding about the gene and the disease.
Fulminant hepatic failure (1 paper, 2012). Hepatic failure refers to the inability of the liver to perform its normal synthetic and metabolic functions, which can result in coagulopathy and alteration in the mental status of a previously healthy individual. "In liver, increased expression of CD40L and its receptor CD40 constitute an early mechanism for liver cell damage in both human and murine fulminant hepatic failure and a recent study has demonstrated that overexpression of hepatic CD40L in mice induces ALF." (PMID 23166746, 2012).
Fulminant hepatitis (1 paper, 2021). Acute hepatitis complicated by acute liver failure with hepatic encephalopathy occurring less than 8 weeks after the onset of jaundice. "Furthermore, in another murine model of fulminant hepatitis, cd40 expression was markedly increased in hepatocytes, so that our observed increase in cd40 gene expression was probably also derived from hepatocytes and not from immune cells exclusively." (PMID 34440067, 2021).
fungal infections (1 paper, 2024). "CD40/CD40L signaling is known to contribute to the adaptive Th1 immune response against fungi, such as Candida albicans, and life-threatening fungal infections were reported in patients deficient in CD40L or CD40." (PMID 39200391, 2024). "Beyond the anti-CD40 IgG4/anti-CD40L PAS-Fab combination therapy, all animals received mycophenolate mofetil as a generally immunosuppressive drug, which is known to increase the risk of fungal infections." (PMID 39200391, 2024).
gastric adenoma (1 paper, 2014). A neoplastic polyp that arises from the stomach. "No positive CD40 mutant staining was observed in the 10 cases of normal gastric tissue or the 10 cases of gastric adenoma." (PMID 24885116, 2014). "No positive CD40 mutant staining was observed in the normal gastric tissue or the gastric adenoma." (PMID 24885116, 2014). "Furthermore, no positive CD40 mutant staining was observed in normal gastric tissues or gastric adenoma tissues, hence there is a possibility that CD40 mutant is considered as a tumor biomarker for differentiating malignant and benign tumors." (PMID 24885116, 2014).
gastric MALT lymphomas (1 paper, 2016). "In gastric MALT lymphomas which have been extensively studied, it is considered that the molecular mechanism involves the stimulation of antigen receptor by autoantigen and co-stimulatory molecule CD40 by H pylori-specific T cells." (PMID 27516932, 2016).
gastrointestinal stromal tumor (1 paper, 2021). "Administration of imatinib after agonistic anti-CD40 antibody activated TAMs, redirected TAMs to antitumor M1 phenotype, by increased TNF and IL-6 production through the NFκB pathway along with decreased IL-10 production in mouse model of gastrointestinal stromal tumor GIST." (PMID 34209679, 2021).
gastroparesis (1 paper, 2010). Paralysis of the muscles of the stomach wall resulting in delayed emptying of the gastric contents into the small intestine. "Plasma and sera from 3 patients suffering from either enteric dysmotility, irritable bowel syndrome (IBS) or gastroparesis were analysed for C-reactive protein (CRP), and for GnRH antibodies and soluble CD40 by ELISA methods." (PMID 20487533, 2010).
glomerulopathies (1 paper, 2023). "The aim of our study was to assess the level of anti-UCH-L1 antibodies and anti-CD40 antibodies as potential factors of podocyte damage in patients with different glomerulopathies, and to evaluate their significance in diagnosis of primary podocyte diseases." (PMID 37409273, 2023). "The aim of the study is to evaluate the levels of anti-CD40 and anti-ubiquitin carboxyl-terminal hydrolase L1 (anti-UCH-L1) antibodies in patients with podocytopathies in comparison with other glomerulopathies." (PMID 37409273, 2023). "The levels of anti-UCH-L1 antibodies were significantly higher in MCD patients and anti-CD40 antibodies were higher in MCD and FSGS than in the control group and other groups of glomerulopathies." (PMID 37409273, 2023). "An increase in the level of anti-UCH-L1 antibodies is specific for steroid-sensitive FSGS and MCD, while an increase in anti-CD40 antibodies – for steroid-resistant FSGS, compared with other glomerulopathies." (PMID 37409273, 2023). "We noted an increase in the level of anti-CD40 antibodies in the serum of patients with FSGS and MCD compared with other forms of glomerulopathies." (PMID 37409273, 2023).
hyperhomocysteinemia (1 paper, 2017). A serious metabolic condition caused by mutations in the MTHFR gene, medications, or nutritional deficiency. "Our recent evidence is shown that metabolic RF, such as uremic toxin or hyperhomocysteinemia, induced immune checkpoint molecule CD40 expression in monocytes (MC) and elevated serum soluble CD40 ligand (sCD40L) resulting in CD40+ MC differentiation." (PMID 28738836, 2017).
hyperparathyroidism (1 paper, 2010). Hyperfunction of the parathyroid glands resulting in the overproduction of parathyroid hormone. "PPR-dependent stimulation of TNF production by T cells and the resulting TNF regulation of CD40 signaling in SCs are potential new therapeutic targets for the bone loss of hyperparathyroidism." (PMID 20808842, 2010).
ileitis (1 paper, 2017). "For example, gene networks associated with ileitis were suppressed ~8% (P < 0.05), and included Cd36, Il4, Cd44, Cd4, and Cd40." (PMID 28446880, 2017).
inflammatory breast carcinoma (1 paper, 2025). An advanced, invasive breast adenocarcinoma characterized by the presence of distinct changes in the overlying skin. "Previous studies conveyed that NF-κβ can dramatically increase the expression of many genes in inflammatory breast cancer, including CD40, IL15, COX2, and CXCL1." (PMID 40035822, 2025).
invasive carcinoma of the breast (1 paper, 2020). "On the other hand, it has been shown that CD40 is significantly correlated with CD40LG gene expression in 529 patients with invasive carcinoma of the breast according to the TCGA (Provisional) data set of the Agilent microarray platform (Pearson correlation: 0.53, P < 0.05)." (PMID 32256143, 2020).
keloid scar (1 paper, 2019). "Using CD40+ and CD206+ (also known as mannose receptor) as markers to identify M1 and M2 macrophages, respectively, we found that both normal skin and keloid scar models were able to induce the M2 phenotype in the co-cultured monocytes." (PMID 31187196, 2019).
kidney failure (1 paper, 2021). An acute or chronic condition that is characterized by the inability of the kidneys to adequately filter the blood. "The only advent of kidney failure, liver failure, and need for pressors was associated with elevation of specific markers (CCL4, CD40, CXCL5, and IL-15), but our findings’ interpretation needs more broad context." (PMID 34177897, 2021).
knee osteoarthritis (1 paper, 2017). "This study explored the association between single nucleotide polymorphisms (SNPs) in the CD40 gene, rs4810485 G > T and rs1883832 C > T, as well as disease susceptibility and severity in knee osteoarthritis (KOA) in the Chinese Han population." (PMID 28320398, 2017).
larynx cancer (1 paper, 2024). A primary or metastatic malignant neoplasm involving the larynx. "Based on this information, our aimed to assess the potential impacts of CD40 (rs1883832) and CD40L (rs1126535) gene polymorphisms on the susceptibility to larynx cancer as well as serum levels of sCD40 and sCD40L proteins to determine their association with larynx cancer." (PMID 39625893, 2024).
lipidosis (1 paper, 2021). "Examination of livers from mice treated with anti-CD40 and then subsequent chemotherapy revealed severe diffuse hepatic lipidosis." (PMID 34101617, 2021).
lung injury (1 paper, 2022). "CD40L expression has occurred in transfusion reactions as per the following previous studies: first, platelets cause transfusion-related acute lung injury via the CD40/CD40L complex." (PMID 35740005, 2022).
lupus erythematosus (1 paper, 2019). An autoimmune, connective tissue chronic inflammatory disorder affecting the skin, joints, kidneys, lungs, heart, and the peripheral blood cells. "In the same line, the rs4810485 SNP was associated with CD40 protein expression on CD14+ monocytes and CD19+ B cells from lupus erythematosus patients assessed by flow cytometry." (PMID 31183392, 2019).
macrophage activation syndrome (1 paper, 2021). A complication of rheumatic disease that is caused by excessive activation and uncontrolled proliferation of T lymphocytes and well-differentiated macrophages. "For instance, in a mouse model of macrophage activation syndrome, liver toxicity upon CD40 mAb ligation was abolished after macrophage depletion or macrophage-selective cd40 gene deletion." (PMID 34440067, 2021).
mucous membrane pemphigoid (1 paper, 2022). Mucous membrane pemphigoid is a bullous dermatosis characterized clinically by blistering of the mucous membranes followed by scarring, and immunologically by IgG, IgA and/or C3 deposits on the epidermal basement membrane. "Additionally, IL-13 exerts profibrotic and proinflammatory effects on the human conjunctival fibroblasts by up-regulating the expression of the T cell co-stimulatory molecules CD80, CD40, and CD154, suggesting a significant role in the pathophysiology in mucous membrane pemphigoid (MMP)." (PMID 35140724, 2022).
muscular dystrophy (1 paper, 2022). Muscular dystrophy (MD) refers to a group of more than 30 genetic diseases characterized by progressive weakness and degeneration of the skeletal muscles that control movement. "In fact, the transition from innate to adaptive immunity, in which CD40 is implicated, is relevant in muscular dystrophy, especially with regards to the balance between macrophages with pro-fibrotic (M1) vs pro-regenerative (M2) phenotype." (PMID 35513612, 2022).
myasthenia gravis (1 paper, 2022). Myasthenia gravis (MG) is a rare, clinically heterogeneous, autoimmune disorder of the neuromuscular junction characterized by fatigable weakness of voluntary muscles. "CD40 signaling is necessary for B-cell activation and antigen-specific antibody production inherent to the development of myasthenia gravis (MG)—the most common disorder of the neuromuscular junction." (PMID 35456932, 2022).
myocarditis (1 paper, 2022). Myocarditis is a condition that is characterized by inflammation of the heart muscle (myocardium). "Furthermore, plasmacytoid DCs from myocarditis patients showed lower percentages of CD40 positive cells (p = 0.01) compared with healthy controls." (PMID 35265721, 2022).
nephrolithiasis (1 paper, 2021). The presence of a calculus in the pelvis of the kidney; this is most often composed of mineral salts and proteins. "Genes in this crosstalk include those previously reported to be of functional relevance to nephrolithiasis, such as protein kinase C (PRKCA, PRKCB, and PRKCZ), markers (CD40 and TLR3), and autophagy (MTOR and SQSTM1), thus validating our genetic prioritization at the gene and pathway level." (PMID 34489936, 2021).
neuritis (1 paper, 2021). A neuropathy arising from inflammation of one or more nerves. "Also, in the animal model of GBS, CD40 is essential in creating EAN in mice; the dramatically increased expression of CD40 and CD40L marks the cooperation of B and T cells in the initiation of neuritis." (PMID 34539561, 2021).
neuropathic pain (1 paper, 2012). Chronic pain caused by damage to nerve fibers. "Our previous studies have indicated that both lumbar spinal cord-infiltrating CD4+ T cells and microglial CD40 contribute to the maintenance of mechanical hypersensitivity in a murine model of neuropathic pain spinal nerve L5 transection (L5Tx)." (PMID 23249743, 2012).
Omenn syndrome (1 paper, 2016). An inflammatory condition characterized by erythroderma, desquamation, alopecia, chronic diarrhea, failure to thrive, lymphadenopathy, and hepatosplenomegaly, associated with severe combined immunodeficiency (SCID). "After considering SCID/Omenn syndrome, other significant or transplantable conditions could be considered such as WAS, IPEX, DOCK8 deficiency, EDA-ID and CD40L/CD40 deficiency and others." (PMID 27222657, 2016).
osteopetrosis (1 paper, 2010). Osteopetrosis, also known as marble bone disease, is a descriptive term that refers to a group of rare, heritable disorders of the skeleton characterized by increased bone density on radiographs. "In vivo evaluation of the genetic deficiency in TRAF6 confirmed its role in CD40-, IL-1-, and LPS signaling and phenotypically resulted in severe osteopetrosis." (PMID 20644648, 2010).
parasite (1 paper, 2017). "The impairment of CD40 expression and IL-12p70 production by DC caused by L. amazonensis is an important immune response evasion mechanism, since both molecules are essential for the development of a Th1 response necessary to control the parasite infection." (PMID 28791011, 2017).
pediatric cancer (1 paper, 2025). "In pediatric cancer, TNF-α has been shown to promote de-differentiation of OS, Furthermore, the immature state of pediatric T-cells has been shown to contribute to reduced expression of CD40, a tumor necrosis factor receptor family member." (PMID 39796780, 2025).
pelvic inflammatory disease (1 paper, 2024). Pelvic inflammatory disease (PID) is an acute or chronic inflammation in the pelvic cavity. "The expression of plasma CD40L is increased in pelvic inflammatory diseases, however, the relationship between CD40 and POP is unclear." (PMID 39902300, 2024).
peripheral nerve injury (1 paper, 2012). Injury to a peripheral nerve. "Altogether, data indicate that both CD4 and CD40 play a role in L5Tx-induced leukocyte infiltration into the lumbar spinal cord but have differential contributions to spinal cord microglial activation following peripheral nerve injury." (PMID 23249743, 2012). "Altogether, our data indicate that both CD4 and CD40 play a role in L5Tx-induced leukocyte infiltration into the lumbar spinal cord but have differential contributions to spinal cord microglial activation following peripheral nerve injury." (PMID 23249743, 2012).
pneumococcal infection (1 paper, 2022). Infections with bacteria of the species streptococcus pneumoniae. "In contrast, reduced CD40 expression by moDCs was observed in all pneumococcal infections." (PMID 35249041, 2022).
podoconiosis (1 paper, 2024). A disease of the lymphatic vessels of the lower extremities that is caused by chronic exposure to irritant soils. "The three DC subsets had significantly higher levels of CD40 expression while expression of CD86 was higher only in myeloid DCs in podoconiosis patients compared to the healthy controls." (PMID 38448477, 2024). "However, the expression of the co-stimulatory molecules CD86 and CD40 among classical monocytes was higher in podoconiosis patients." (PMID 38448477, 2024). "Evaluation of the activation biomarkers within the three subsets showed that the expression of CD40 was significantly higher in all three DC subsets, in particular on mDCs, in podoconiosis patients compared to healthy controls (median value of 8.4% vs 3.7%, respectively, P = 0.003)." (PMID 38448477, 2024). "The expression of HLA-DR, CD40, CD86, and CD36 was analyzed on monocytes from 43 podoconiosis patients and 34 healthy controls." (PMID 38448477, 2024). "Expression of the activation markers CD40 and CD86 was significantly higher on classical monocytes from podoconiosis patients compared to healthy controls, with median values of 35.6% vs 25.5% for CD40 and 13.7% vs 7.4% for CD86 (P = 0.03, P = 0.001, respectively)." (PMID 38448477, 2024).
polymyositis (1 paper, 2024). A rare idiopathic inflammatory myopathy characterized by symmetric proximal muscle weakness and elevated muscle enzymes. "Among these, CD11c on granulocytes, CD40 on monocytes, and HLA-DR+ NK AC demonstrated protective effects against polymyositis." (PMID 39470507, 2024).
polyp (1 paper, 2016). A usually exophytic mass attached to the underlying tissue by a broad base or a thin stalk. "IL-12 also significantly induced the expression of CD40 L on CD8+ T cells in polyp tissues (P < 0.01)." (PMID 27468819, 2016).
primary biliary cirrhosis (1 paper, 2021). "Interestingly, autoimmune cholangitis was transiently delayed by CD40 activation in a murine model of primary biliary cirrhosis, which expresses a dominant form of transforming growth factor-β receptor type II." (PMID 34440067, 2021).
primary progressive multiple sclerosis (1 paper, 2024). A multiple sclerosis that is characterized by steady worsening of neurologic functioning, without any distinct relapses or periods of remission. "The objective of this study was to investigate regulatory T cells (Tregs) and monocytes; specifically, the expression of CTLA-4 (CD152) and FOXP3+ in CD4+CD25+ Tregs and the expression of CD40+ and CD192+ monocyte subpopulations in subjects with primary progressive multiple sclerosis (PPMS)." (PMID 38398067, 2024).
primary sclerosing cholangitis (1 paper, 2007). "Stronger staining was seen in liver tissue from patients with primary sclerosing cholangitis (PSC) where the inflammatory infiltrate, sinusoidal endothelium and ductules stained positively for CD40 and periportal hepatocytes and inflammatory cells for C4BP." (PMID 17225862, 2007).
pulmonary edema (1 paper, 2019). Accumulation of fluid in the lung tissues causing disturbance of the gas exchange that may lead to respiratory failure. "We also showed that CD40/CD40L inhibition is effective in the prevention of pulmonary edema." (PMID 31467410, 2019). "Inhibition of the CD40/CD40L immunomodulator interaction significantly reduced communication between immune and/or endothelial cells and the development of pulmonary edema." (PMID 31467410, 2019).
reovirus infection (1 paper, 2013).
retinal ischemia (1 paper, 2019). A ischemic disease that involves the retina. "The CD40-ATP-P2X7 pathway not only amplifies inflammation but also induces death of retinal endothelial cells, an event key to the development of capillary degeneration and retinal ischemia." (PMID 31921199, 2019).
schwannoma (1 paper, 2022). A benign, usually encapsulated slow growing tumor composed of Schwann cells. "CD40, CD11c, and S100 antibody scoring were identical between GCTs and schwannomas." (PMID 35323240, 2022). "Immunoreactivity to CD68, HLA-DR, CD163, CD40 and CD11c (APC phenotype) and markers of neural crest cell (NCC) origin S100, SOX10, NSE and GAP43 in 23 cases of GCTs and 10 cases of Schwannomas were evaluated." (PMID 35323240, 2022). "This study aims to differentiate an antigen-presenting cell (APC) phenotype from a neural tissue phenotype in GCTs using immunohistochemistry (HLA-DR, CD68, CD163, CD40 and CD11c for APC), and polymerase chain reaction and to compare this expression profile with schwannomas." (PMID 35323240, 2022). "CD40 and CD11c: Schwannomas and GCTs had no CD40 and CD11c immunoreactivity." (PMID 35323240, 2022).
Senile plaques (1 paper, 2011). Senile plaques are extracellular deposits of amyloid in the gray matter of the brain. "Also in AD brain, aggregates of reactive microglia express CD40 in senile plaques." (PMID 21223591, 2011).
sensitization (1 paper, 2014). "SNPs in or near JAK2, CNOT6, MAML1, CD40, IL-4R, and IL-5RA genes were associated with allergic sensitization and SNPs in or near JAK1, JAK3, IL5RA, FCER1A, and ADAM33 genes were associated with cockroach sensitization." (PMID 25505553, 2014).